PDCD1 (programmed cell death 1)
Diseases named in the same sentence as PDCD1 in open-access papers (continued):
Sharing a sentence is not in itself a finding about the gene and the disease.
cancer (continued). "For example, combination therapy with immune checkpoint inhibitors of cytotoxic T lymphocyte-associated protein 4 (CTLA) and programmed cell death 1 (PDCD1, also known as PD1) has shown effective clinical application potential in the treatment of cancer (Liu J.-N." (PMID 33987201, 2021). "In addition, blocking of programmed cell death-1 (PD-1)/programmed cell death ligand-1 (PD-L1) has become a major cancer immunotherapy in various human cancers including NSCLCs." (PMID 34576028, 2021). "However, the relationship between the expression of soluble programmed cell death-1(sPD-1) and cancer pain is controversial." (PMID 33907102, 2021). "Recently, targeting programmed cell death 1 (PD-1)/programmed cell death ligand 1 (PD-L1) immune checkpoint inhibitors have led to major progress in cancer immunotherapy; resulting in positive outcomes in clinical trials across various solid malignancies, including gastric carcinomas." (PMID 32498695, 2020). "Since the discovery and understanding of Programmed Cell Death 1 (PD-1)/Programmed Cell Death Ligand 1 (PD-L1) interactions between cancer and immune cells, blocking the PD-1/PD-L1 interaction has become a novel therapeutic strategy in cancer treatment." (PMID 33204603, 2020). "Immune checkpoint blockade (ICB) using monoclonal antibodies (mAbs) specific to cytotoxic T lymphocyte antigen 4 (CTLA-4) and to programmed cell death 1 (PD-1) or its ligands has emerged as one of the most promising approaches in cancer immunotherapy to invigorate antitumor immunity." (PMID 32998971, 2020). "For example, MMP2/9 highly correlated with exhausted T cell marker PDCD1 across 23 cancer types." (PMID 32988398, 2020). "Cancer immunotherapy has been revolutionized by the development of monoclonal antibodies (mAbs) that inhibit interactions between immune checkpoint molecules, such as programmed cell-death 1 (PD-1), and its ligand PD-L1." (PMID 32455628, 2020). "Furthermore, blocking both TIM-3 and programmed cell death 1 (PD1) can improve antitumor T cell responses in patients with advanced cancers." (PMID 32660524, 2020). "Furthermore, TAMs upregulate the programmed cell death 1 (PD-1) expression forming a local immunosuppressive microenvironment, thus facilitating the immune escape of cancer cells." (PMID 32711514, 2020). "The combined administration of programmed cell death 1 (PD-1) and programmed cell death ligand 1 (PD-L1) inhibitors might be considered as a treatment for poorly responsive cancer." (PMID 31022941, 2019). "Cancer immunotherapy with immune checkpoint inhibitors has been the focus of many studies since the efficacy of immunotherapy targeting the immune checkpoint molecule programmed cell death-1 (PD-1) and its ligand PD-L1 was demonstrated." (PMID 31221178, 2019). "Immune checkpoint inhibitors block negative co-stimulatory signals such as programmed cell death-1 and cytotoxic T-lymphocyte-associated protein 4, ultimately reactivating anti-cancer immunity." (PMID 31521196, 2019). "However, cancer cells have immune escape mechanisms, such as the programmed cell death-1 (PD-1)/PD-1 ligand (PD-L1) pathway." (PMID 31623180, 2019). "Programmed cell death 1 (PD-1) is an inhibitory receptor expressed mainly by activated T cells and its ligand, PD-L1, is widely expressed in cell types as diverse as epithelial cells, immune cells, and cancer cells." (PMID 31192215, 2019). "Although blocking of programmed cell death-1 (PD-1) alone has shown great promise in the treatment of advanced solid tumors, combined immunotherapies will be required to efficiently treat a wider range of cancer patients." (PMID 30026742, 2018). "Cancer cells can express ligands for T cell inhibitory receptors such as PDCD1 (PD-1) (ligand is CD274 [PD- L1]), CTLA-4 (ligands are CD80 and CD86), and HAVCR2 (aka TIM3) (ligand reported to be GAL9) to inhibit T cell activation and cytolytic T cell responses." (PMID 28822103, 2018).
cancer (continued). "Treatment strategies of this sort mainly attempt the reconstitution of host immune surveillance that is otherwise suppressed by cancers, where the monoclonal antibodies targeting on programmed cell death 1 (PD-1) and PD-1 ligand (PD-L1) are by far the most successful instance." (PMID 29483918, 2018). "Programmed cell death ligand-1 (PD-L1), also known as B7-H1 and CD274, functions by interacting with its cognate receptor programmed cell death-1 (PD-1) to negatively regulate T cell functions, and therefore plays a pivotal role in the immune evasion of many cancer types." (PMID 30373602, 2018). "Programmed cell death 1 (PD-1) is a key target for cancer immunotherapy." (PMID 28165004, 2017). "Blockade of immune checkpoints, such as cytotoxic T-lymphocyte antigen-4 (CTLA-4) and programmed cell death-1 (PD-1)/ programmed cell death ligand-1 (PD-L1) signaling, have demonstrated broad anti-cancer activities with an acceptable side effect profile in different cancer types, including NSCLC." (PMID 28460468, 2017). "The PD-L1 ligand of programmed cell death 1 (PD-1) is upregulated in various types of cancers." (PMID 29383103, 2017). "Programmed cell death 1 (PD-1) and its ligand 1 (PD-L1) inhibitors have quickly become standard of care for patients with advanced non-small cell lung cancer and increasing numbers of other cancer types." (PMID 28245875, 2017). "Blocking interaction between the programmed cell death-1 protein and its ligand PD-L1 is reported to produce extraordinary antitumor responses, and researchers in a number of clinical trials are assessing the prognostic relevance of PD-L1 in cancers." (PMID 27363678, 2016). "The interaction of programmed cell death-1 and its ligand is widely studied in cancer." (PMID 26943572, 2016). "After reading the title and the abstracts of these studies, 555 studies were excluded for not reporting the association between the PDCD-1 polymorphisms and cancer risks reviews." (PMID 27749524, 2016). "Also, we found co-expression of FAP and PDCD1 in 22 different cancer types (P < 0.05)." (PMID 39870619, 2025). "However, when patients were simultaneously stratified according to EMT and PDCD1 status, we identified a statistically significant reduction in overall survival for patients with cancer cells having M/high PDCD1 signatures, relative to those with E/low-PDCD1 signatures." (PMID 40631902, 2025). "ICRs such as programmed cell death 1 (PD-1) and T cell immunoglobulin and mucin domain-3 (Tim-3) are classic CD8+ T cell exhaustion markers implicated in chronic viral infections like HIV-1 and certain cancers, and their co-expression is thought to represent the most severely exhausted phenotype." (PMID 40875618, 2025). "Strikingly, ACACA expression exhibited significant negative correlations with the immune checkpoint-related genes (PDCD1, LAG3, LAGLS9, IDO1, CD244, CTLA4 and TIGIT), while showing positive associations with other genes (TGFBR1, KDR, IL10RB, CD160 and CD274) across most cancer types." (PMID 41169354, 2025). "Recently, immune checkpoint blockade (ICB) therapy using anti-programmed cell death-1 (PD-1)/PD-1 ligand (PD-L1) antibodies have not only achieved remarkable benefits in the clinical management of ESCC but have also completely changed the treatment approach for this cancer." (PMID 38440724, 2024). "In addition, PDCD1 demonstrated a very high positive correlation with sensitivity in docetaxel, suggesting that this drug could be used successfully to treat cancer, alone or in combination with ICIs like pembrolizumab and nivolumab." (PMID 39064019, 2024). "Additionally, PDCD1 is an inhibitory regulator of T-cell activation, which may hurt the elimination of cancer cells." (PMID 36983159, 2023).
cancer (continued). "A recent meta-analysis study revealed that Asian cancer patients receiving PD-1/PD-L1 (programmed cell death 1)/(programmed death-ligand 1)-inhibitor-based therapy may experience a significantly improved benefit in terms of survival rate when compared to non-Asian patients." (PMID 36675289, 2023). "ICIs target programmed cell death-1 (PD-1), PD ligand-1 (PD-L1), and cytotoxic T-lymphocyte-associated antigen-4 (CTLA-4), with a subsequent disruption of the host T cell signaling and the upregulation of the T cell immune innate and adaptive response against cancer cells." (PMID 37175898, 2023). "Moreover, MTHFD2 was discovered to be positively associated with several immune checkpoints, such as cytotoxic T lymphocyte-associated antigen-4 (CTLA-4), PD-L1, T-cell immunoglobulin and mucin domain-3 (TIM-3), and Programmed Cell Death 1 (PD-1) in most cancers, especially in BLCA." (PMID 38130721, 2023). "Immune checkpoint blockades (ICBs), especially the inhibitors targeted to programmed cell death-1 (PD-1) or programmed death-ligand 1 (PD-L1), which can release the brakes of the hosts’ immune system to achieve durable clinical responses, have resulted in a transformation of cancer treatment." (PMID 36980323, 2023). "Additionally, In the cancer patients treated with anti-PDCD1 (Pembrolizumab), anti-CD274 (Atezolizumab), or anti-CTLA4 (Ipilimumab) of the K-M plotter database, elevated KLRB1 expression exhibited better OS and progression-free survival (PFS) after grouping with KLRB1 expression median value." (PMID 37988189, 2023). "In pathway analysis and cancer immune correlation analysis, we observed that SRSFs were associated with the activation or inhibition of multiple immune pathways, and were also closely related to the expression of multiple immune checkpoints (LAG3, CD274, CTLA4, TIGIT, PDCD1)." (PMID 38015716, 2023). "Programmed cell death 1 (PD1): programmed cell death 1 ligand 1 (PDL1), and cytotoxic T lymphocyte-associated protein 4 (CTLA4): B-lymphocyte activation antigen B7 (B7-1; also termed CD80) are the most extensively studied immune checkpoints for cancer immunotherapy." (PMID 35493449, 2022). "Programmed cell death 1 (PD-1) is a transmembrane glycoprotein that, when engaged by its ligands (PD-L1 and PD-L2), is expressed by antigen-presenting cells (APC), cancer cells and cancer cell-associated fibroblasts, inhibiting kinases that are involved in T-cell activation." (PMID 35681761, 2022). "Emerging work has shown that immune checkpoint blockade (ICB) therapy is effective against advanced human cancer; however, only a small subset of cancer patients could benefit from anti-programmed cell death-1/programmed death ligand 1 (anti-PD-1/PD-L1) immunotherapy." (PMID 36713584, 2022). "Targeting immune-checkpoint molecules, such as programmed cell death 1 (PD-1), programmed cell death ligand 1 (PD-L1) and cytotoxic T-lymphocyte-associated protein 4 (CTLA-4), has also demonstrated to be one of the most promising cancer treatments, with positive results in KRAS-mutated cancers." (PMID 35883626, 2022). "However, programmed cell death 1 (Pdcd1), proprotein convertase subtilisin/kexin type 2 (Pcsk2), and LHFPL tetraspan subfamily member 3 (Lhfpl3) are known to be associated with cancer development." (PMID 35565312, 2022). "The admission of immune checkpoint inhibitors [e.g., anti-programmed cell death-1/programmed cell death ligand 1 (PD-1/PD-L1) antibodies] in primary and advanced cancer had a striking effect on progressive-free survival, overall survival, and objective response rates on various types of cancer." (PMID 35463364, 2022). "Therefore, this system shows great potential for testing immune-oncology therapies, including programmed cell death-1 (PD-1)/PD-ligand 1 (PD-L1) blockade and T-cell therapies for cancer patients within a time frame that is suitable for guiding cancer treatment in the clinic." (PMID 39036550, 2022).
cancer (continued). "Notably, CD274/PD-L1, PDCD1LG2/PD-L2, PDCD1/PD1, cytotoxic T lymphocyte-associated antigen 4 (CTLA4), T cell membrane protein 3 (TIM3; also known as HAVCR2), and lymphocyte activation gene 3 (LAG3) were correlated to FAM72A across different cancers." (PMID 36613817, 2022). "Programmed cell death 1 (PD-1) is expressed on activated T cells, B cells, monocytes, and macrophages, the interaction of PD-L1 with its receptor PD-1 inhibits T-cell responses, and a blockade of this interaction has been proven to be an effective immunotherapy for several different cancers." (PMID 35967399, 2022). "In recent years, the field of cancer immunotherapy has seen considerable progress due to the discovery of new therapies targeting immune checkpoint molecules such as cytotoxic T lymphocyte-associated protein 4 (CTLA-4), programmed cell death 1 (PD1) and programmed cell death ligand 1 (PD-L1)." (PMID 35840912, 2022). "Via the programmed cell death 1 (PD-1) signaling pathway, the release of negative regulators of immune activation (immune checkpoints) restricts antitumor responses and leads to unparalleled rates of persistent tumor responses in patients with multifarious cancers." (PMID 34645484, 2021). "Alternative splicing can generate different isoforms that are expressed at similar levels after T cell activation; however, genetic variants at PDCD1 coding and regulatory 5’ and 3’ untranslated regions (UTR) may influence protein levels and the natural history of cancer development." (PMID 34290992, 2021). "Novel therapy targeting immune checkpoints, such as programmed cell death 1 (PD1)/programmed cell death 1 ligand 1 (PD-L1), cytotoxic T-lymphocyte associated protein 4 (CTLA4) and T-cell membrane protein 3 (TIM3) have made breakthrough in many types of cancer treatment." (PMID 34249934, 2021). "Immune checkpoint inhibitors, including anti-programmed cell death 1 (PD-1), anti-programmed cell death ligand 1 (PD-L1) monoclonal antibodies (MAbs) and CTL-associated antigen 4 (CTLA4) blockade have been confirmed to improve the overall survival rate of patients in different cancer types." (PMID 34326840, 2021). "ICIs are an important method of cancer immunotherapy and are aimed at blocking several targets that interfere with the proliferation of T-lymphocytes, such as cytotoxic T-lymphocyte-associated protein 4 (CTLA-4), programmed cell death 1 (PD-1), programmed cell death ligand 1 (PD-L1)." (PMID 33348704, 2020). "Although novel strategies using an immune-checkpoint inhibitor (ICI), such as anti-programmed cell death-1 antibody, have been clinically proven to be effective in many types of malignant tumors, such strategies may be insufficient to prevent regrowth in recurrent GBM." (PMID 32707672, 2020). "In the constantly evolving era of immunotherapy, blockade of the programmed cell death 1 (PD-1)/programmed cell death ligand-1 (PD-L1) immune checkpoint pathway represents one of the most promising strategies regarding reverting immune evasion in the cancer immunoediting process." (PMID 33204263, 2020). "Notably, the blockade of immunosuppressive checkpoints, such as T-lymphocyte-associated antigen 4 (CTLA4), programmed cell death 1 (PD1) protein, and programmed cell death-ligand 1 (PD-L1), has demonstrated objective clinical responses in various cancers and other malignant neoplasms." (PMID 30871634, 2019). "We further found that ITGA4 was positively correlated with most immune regulatory molecules across cancers, such as CTLA4, PDCD1, LAG3, which inhibit T cell activity." (PMID 40012546, 2025). "Checkpoint inhibitors such as anti-PDCD1/PD-1 and anti-CTLA4 antibodies block inhibitory pathways in T cells, enhancing their activity against cancer cells." (PMID 39817564, 2025). "Further analyses showed that these high HLA‐DR+ cancer cell tumors exhibited elevated levels of LAG3, TNFRSF9, CTLA4, PDCD1, TIGIT, ITGB2, and GZMB." (PMID 40464412, 2025).
cancer (continued). "The correlation between SLC2A1 expression and eight immune checkpoints (CTLA4, PDCD1, TIGIT, LAG3, CD274, HAVCR2, PDCD1LG2, and SIGLEC15) was further investigated across multiple cancer types." (PMID 40824962, 2025). "The mRNA expression profile of six Tex markers, LAG-3, PDCD1, TIGIT, HAVCR2, CXCL13, and LAYN was investigated in pan-cancer." (PMID 40076932, 2025). "Our research shows that PIEZO1 expression is positively correlated with key immune checkpoints, including CD274 (PD-L1), CTLA4, LAG3, PDCD1 (PD-1), PDCD1LG2 (PD-L2), and TIGIT across various cancer types." (PMID 40977743, 2025). "In line with increased infiltration of cluster #2 cancers by T cells, clinically relevant immune checkpoint genes CTLA4, TIGIT, and PDCD1 were found to be expressed in this cluster at the highest levels." (PMID 40011822, 2025). "The programmed cell death 1 (PD1) can be regarded as the primary immune checkpoint and antibodies targeting PD1 or its ligand PDL1 have revolutionized immunotherapy of cancer." (PMID 40119938, 2025). "In the PD1 and PD-L1 cancer immunotherapy pathway, downregulation of CD247, PDCD1, and CD28 gene expression and upregulation of CD274 and miR-3614-5p were measured." (PMID 38571958, 2024). "Not only that, our results also reveal a positive correlation between LAPTM4A and multiple immune checkpoint (ICP) gene expressions, including the well-known CD274, PDCD1, and CD80, which tend to suppress effector T cells to promote cancer development." (PMID 38613802, 2024). "We investigated the methylation levels (beta values) of TIGIT, CXCL13, LAYN, LAG3, PDCD1, and HAVCR2 across different cancer types." (PMID 39064019, 2024). "Checkpoint inhibitor therapy is a form of cancer immunotherapy targeting Cytotoxic T-Lymphocyte Antigen 4 (CTLA4), programmed cell death-1 (PD-1), and programmed cell death-ligand 1 (PD-L1) to restore immune system function." (PMID 39034992, 2024). "Representative immunotherapeutic modalities, especially checkpoint proteins such as programmed cell death 1 (PD-1) and cytotoxic T lymphocyte antigen 4 (CTLA-4) have achieved great success in some type of cancers in clinical settings." (PMID 38571953, 2024). "Further, NMUR1 was positively associated with a spectrum of immune cells, notably CD8+ T cells and NK cells, and immune inhibitors such as PDCD1 and CTLA4, across diverse cancers." (PMID 39055918, 2024). "Lastly, we conducted a pan-cancer analysis, revealing significant correlations between ALPK1 and various immune checkpoints, including PD-L1, CTLA-4, LAG-3, and PDCD1." (PMID 39845963, 2024). "Subsequently, we also explored the correlation between the expression levels of LRP6 and the expression levels of common immune checkpoints in 33 cancers, such as SIGLEC15, IDO1, CD274, HAVCR2, PDCD1, CTLA4, LAG3 and PDCD1LG2." (PMID 38226972, 2024). "Immune checkpoint inhibitors (ICIs) are cancer therapies that activate the host immune response by blocking immune suppressive signaling pathways, such as cytotoxic T-lymphocyte antigen (CTLA-4), programmed cell death 1 (PD-1), and ligand." (PMID 39264061, 2024). "In the radar plots analyzing correlations between gene expression and TMB and MSI, CCR8, CD274, and PDCD1 expression levels showed significant positive correlations with TMB and MSI in several cancer types." (PMID 39273290, 2024). "ICI is a monoclonal antibody antagonist that increases the body’s immune response to cancer cells by blocking intrinsic immune response downregulators, such as CTLA-4 and programmed cell death 1 (PD-1) or its ligand programmed cell death ligand 1 (PD-L1)." (PMID 38676836, 2024). "We initially explored the expression of the Tex signature genes (LAG3, TIGIT, LAYN, PDCD1, HAVCR2, and CXCL13) in pan-cancer." (PMID 39064019, 2024). "Then, immune checkpoints analysis shown that UBE2C had a negative correlation with immune checkpoints, such as CD274(PD-1), PDCD1(PD-L1), CTLA4, TIGIT, LAG3, HAVCR2, and PDCD1LG2 in a great many cancers." (PMID 38370368, 2024).